C1orf87 (chromosome 1 open reading frame 87)
Synonyms: MGC34837; CREF
Tractability: No criterion of Open Targets' tractability assessment is met for any kind of drug.
Gene: Protein-coding gene on chromosome 1 (59,987,269 to 60,073,770, reverse strand). Ensembl gene ENSG00000162598.
Subcellular location: Cell projection, cilium; Cytoplasm, cytoskeleton, cilium axoneme
Gene Ontology:
Cellular component: axoneme; cilium
Genetic constraint (gnomAD): Loss-of-function variants: 43 observed, 48.01 expected, observed/expected ratio (o/e) 0.9, 90% interval 0.7 to 1.15. The upper end of that interval is the gene's LOEUF score, 1.15, which puts it in group 5 of 6, group 1 being the genes least tolerant of losing a copy. Missense variants: 601 observed, 595.41 expected, observed/expected ratio (o/e) 1.01, 90% interval 0.94 to 1.08. Synonymous variants: 215 observed, 218.81 expected, observed/expected ratio (o/e) 0.98, 90% interval 0.88 to 1.1.
Homologues: Orthologues: chimpanzee C1H1orf87 (99% identical), macaque C1H1orf87 (94% identical), dog C1orf87 (73% identical), pig C1orf87 (73% identical), mouse Gm12695 (64% identical), rat C5h1orf87 (61% identical).
Diseases named in the same sentence as C1orf87 in open-access papers:
C1orf87 is named in the same sentence as 2 diseases in open-access papers, as found by Europe PMC text mining. Sharing a sentence is not in itself a finding about the gene and the disease. The quoted sentences say what the papers report.
Cognitive impairment (1 paper, 2016). Abnormal cognition is characterized by deficits in thinking, reasoning, or remembering. "Furthermore, patient DCP300407 with only HOOK1, CYP2J2 and C1orf87 deleted displays cognitive impairment." (PMID 26997977, 2016).
C1orf87 also shares sentences with these, for which no sentence is quoted: periodontitis (1 paper).